MTOR (mechanistic target of rapamycin kinase)
Diseases named in the same sentence as MTOR in open-access papers (continued):
Sharing a sentence is not in itself a finding about the gene and the disease.
infection (continued). "A total of 16 circRNAs and five lncRNAs combined to form two ceRNA networks, which regulate the mTOR pathway through miR-204a, thereby resisting infection." (PMID 39452097, 2024). "In summary, our study reveals an IFN-γ-induced mechanism of host resistance to T. gondii, characterized by suppression of CD115-dependent mTOR signaling in macrophages at the site of infection and potential the sites of parasite dissemination." (PMID 38377133, 2024). "Both egg drop syndrome virus (EDSV) infection of duck embryo fibroblasts (DEF) cells and orf virus (ORFV) infection of ovine foetal turbinate (OFTu) cells down-regulate PI3K/AKT/mTOR to induce autophagy." (PMID 39227990, 2024). "As infection progresses, activation of the mTOR/AKT pathway can impair glycolysis and mitochondrial metabolism in macrophages, making them more susceptible to M. tb cytotoxicity." (PMID 39457551, 2024). "Toll-like receptor (TLR) and host cytokine signaling inresponse to infection activate mTOR through the PI3K/Akt pathway, with downstreameffects on immune effector function." (PMID 38767353, 2024). "As a sensor of cellular homeostasis, mTOR activity is often perturbed during infection, as intracellular pathogens induce amino acid starvation to trigger autophagy." (PMID 38399700, 2024). "Up to now, some factors can regulate this molecule such as starvation, oxidative stress, energy stress, and pathogen infection by phosphorylation for the inhibition of mTOR." (PMID 38932206, 2024). "Next, we aimed to assess the physiological impact of metabolic reprogramming in macrophages via the re-activation of mTOR in response to infection in vivo." (PMID 39349819, 2024). "Combining these observations with invitro experiments confirming similar p65 nuclear translocation, ourdata support a cooperative but separate role of mTOR signaling from NF-κBsignaling within phagocytes in response to infection." (PMID 38767353, 2024). "Alterations within the mTOR pathway can impact both host immune responses and metabolic adaptations to infection." (PMID 39457551, 2024). "SARS-CoV-2 activated the PI3K/Akt/mTOR signaling during the initial phases of infection, which supported the theory of AXL as an early warning indicator for clinical deterioration." (PMID 38799467, 2024). "As expected, we noticed a significantly higher increase with the highly virulent SS strain at both 3 h (1.7 ± 0.3-fold) and 24 h (2.3 ± 0.5-fold) post-infection in mTOR phosphorylation compared with the mock-infected controls." (PMID 38399700, 2024). "We have observed that a reduction in miR-126 transcript alters normal macrophage phenotype and function through its involvement in the Cxcl12/Ccl2/Ccr2 axis and coupled with concurrent mTOR inhibition, increases cell death at the site of infection." (PMID 38307625, 2024). "Based on the results, the mRNA level as well as PI3K, Akt and mTOR expressions were decreased in the infection group compared to the control group (p < 0.01)." (PMID 38582846, 2024). "In the case of APEC infection at 15 days post-hatch, mTOR protein kinase was upregulated by monensin (vehicle and early infection, *, p<0.05, each) and doxycycline (early infection, *, p<0.05)." (PMID 39721265, 2024). "It was also found that in a controlled infection setting, the inhibition of mTOR resulted in a dose-dependent increase in M. tb growth." (PMID 39457551, 2024). "Suppression of mTOR with Rapa also severely inhibited theresolution of infection, as seen on day 12 where recovered CFU counts remainedsignificantly higher in Rapa-treated mice (P < 0.0001)." (PMID 38767353, 2024). "We used whole-mount embryo immunofluorescent staining of phosphorylated ribosomal protein S6 (phospho-S6) as a readout for mTOR activity after infection of miR-126 and tsc1a knockdown embryos with M. marinum." (PMID 38307625, 2024).
infection (continued). "Further investigation of how mTOR signalingfunctions during infection in the context of metabolic disease states such asdiabetes is of considerable clinical interest." (PMID 38767353, 2024). "It has been suggested that SARS-CoV-2 activates the mTOR (mammalian Target Of Rapamycin) pathway during infection." (PMID 39334742, 2024). "Autophagy induction is triggered through distinct signaling cascades under starved conditions and pathogen infection phage that results in the repression of the mammalian target of rapamycin (mTOR)." (PMID 37180758, 2023). "Nevertheless, further studies are required to validate the role of mTOR-regulated necroptosis in other pathogen infections, such as SARS-CoV-2." (PMID 38164133, 2023). "In fact, AMPK and mTOR are tightly interlinked pathways that act in opposition, the AMPK/mTOR, and AKT/mTOR pathway appears to be impacted by infection." (PMID 37407986, 2023). "WBP2 is a gene involved in many signaling pathways, including the PI3K/Akt/mTOR signaling pathway, and has been shown to be downregulated in pig macrophages after infection with porcine reproductive and respiratory syndrome virus." (PMID 37872508, 2023). "Our findings revealed a decrease in PI3K from 24 h after infection, and a decrease in mTOR and phospho-mTOR from 48 h p.i.." (PMID 37026095, 2023). "Further, siRNA knockdown of Rheb, a GTPase that activates mTOR, confirmed a role for mTOR signaling during infection." (PMID 36960039, 2023). "The infection of Trueperella pyogenes induced the expression of mTOR and subsequently inhibited the autophagy of host liver cell." (PMID 36844408, 2023). "To confirm our observation, we analysed the activated mTOR, i.e., phospho-mTOR upon H37Rv infection." (PMID 37590294, 2023). "We found decreased phospho-TFEB and increased TFEB with LC3-II levels in mTOR inhibited condition of NCoR1 KD mo-MΦ at 2 h and 24 h post H37Rv infection." (PMID 37590294, 2023). "Immunosuppression that includes calcineurin inhibitors, mTOR inhibitors, cell cycle inhibitors, and steroids in LTRs had a profound impact on mediators, such as cytokines, which result in infection and or acute rejection." (PMID 37896822, 2023). "The mTOR signaling pathway was also significantly enriched in the 20 °C HIRRV infection group, while we noticed that the majority of DEPPs were enriched in apoptosis in the antiviral immune response." (PMID 37627029, 2023). "Reduction in mTOR signaling also reduces myeloid-derived suppressor cell production, also thought to play a role post-irradiation immune suppression against infection." (PMID 37404812, 2023). "It promotes the downregulation of PI3KC3, Beclin 1, and the mammalian target of rapamycin (mTOR), which, in turn, promotes autophagy, lysosomal degradation, and antigen presentation—essential components of the pre-infection defense mechanism." (PMID 37299555, 2023). "From the haplotype effect perspective (both for 2- and 7-day infection), the DEGs were highly clustered in the “Metabolic”, “Ubiquitin mediated proteolysis”, “Wnt signaling pathway” and “mTOR signaling” pathway." (PMID 37327235, 2023). "Indicative of the shortcomings of the synthetic mycolactone model to determine its role during the early stages of infection, we found significant differences in autophagy induction and mTOR modulation by synthetic mycolactone and bacterial mycolactone." (PMID 35401531, 2022). "A comparison of host gene expression signatures upon infection with the EBOV strain Makona revealed the importance of mammalian target of rapamycin (mTOR) signalling in EBOV infection." (PMID 34919035, 2022).
infection (continued). "Previous studies have shown that Dectin–1 signaling, Akt and mTOR activation are essential for induction of the immune trained phenotype and increased resistance to infection." (PMID 35693816, 2022). "Akt/mTOR/p70S6K pathway plays a vital role in regulating immune function and protein translation in response to environmental stress, such as infection." (PMID 36059479, 2022). "In a study using LCMV Armstrong infection, treatment of mice with the mTOR inhibitor rapamycin enhanced not only the quantity but also the quality of LCMV-specific CD8+ T cells." (PMID 36846018, 2022). "Upon application of network-based system biology methods, negative coordination of the biological signaling systems like FOXO/Notch axis and Akt/mTOR/HIF-1 signaling with metabolic pathways during CCHFV-infection were observed." (PMID 35437144, 2022). "During infection, mTOR maintains an anti-inflammatory environment through bidirectional regulation of NF-ĸB activity through IKKβ." (PMID 36061862, 2022). "Dengue NS5 protein binds to mTOR, suggesting that the viral protein modulates mTOR signaling during infection." (PMID 36171757, 2022). "Infection-induced increases in mTOR activity are adaptive, facilitating rapid increases in mitochondrial energy production, which appear to protect against this mycobacterium-mediated lethal mitochondrial damage." (PMID 36103894, 2022). "Previously, we provided evidence that blockade of mTOR signaling prevented MPLA-mediated macrophage reprogramming as well as MPLA-induced infection resistance." (PMID 36439136, 2022). "Phosphorylation changes in the 5′ adenosine monophosphate-activated protein kinase (AMPK), and pathway modification in insulin/mammalian target of rapamycin (mTOR) have also been reported in chicken muscle after 3 weeks of infection with S. Typhimurium." (PMID 36365008, 2022). "Infection is another common AE of mTOR inhibitors that is characterized by pyrexia, diarrhea, nasopharyngitis, and upper respiratory tract infections." (PMID 35246210, 2022). "By applying network-based system biology methods, we identified the negative co-ordination of the biological signaling systems like FoxO/Notch axis and mTOR/HIF-1 signaling along with metabolic pathways of CCEM during CCHFV-infection at the system level." (PMID 35437144, 2022). "Infection of shAtg16L1 macrophages with M. smegmatis or BCG resulted in significantly decreased autophagy induction but maintained mTOR activation as measured by p-S6." (PMID 36104771, 2022). "A previous study showed that Mtb inhibits mTOR-dependent autophagy and enhances bacterial survival by using efflux systems such as CtpF to pump Ca2+ into macrophages during the early stages of infection (1–4 h)." (PMID 35682696, 2022). "Our system biology analysis further indicated the coordinating role of the metabolic pathways of CCEM with biological signaling systems like Notch/FoxO axis and mTOR/HIF-1 signaling during the CCHFV-infection." (PMID 35437144, 2022). "During SGIV infection, the level of phosphorylated mammalian target of rapamycin (mTOR) was increased with infection time, suggesting that SGIV inhibited autophagy through decreasing in mTOR activity to some extent." (PMID 35432224, 2022). "Herein, mTOR mRNA expression was downregulated in groups supplemented with omega-3 NPs post-infection, which is in line with induction of autophagy." (PMID 36009242, 2022). "As the results showed, compared with those in the mock infection condition, the levels of p-mTOR in PTCs were all significantly decreased 6 h, 12 h, and 24 h post-PPV infection." (PMID 35505413, 2022). "As predicted, this is due to synthetic mycolactone’s ability to inhibit mTOR, as measured by p-S6 and p-Akt (Ser473) accumulation, during infection." (PMID 35401531, 2022). "At the late stage of infection, autophagy is activated by inhibition of the PI3K/Akt/mTOR pathway, which is mediated by the M protein encoded by BEFV." (PMID 35402295, 2022).
infection (continued). "Although previous studies have explored immunological dysfunction during burn injury, no study has established a mechanistic link between the immune dysfunction, subsequent infection control, and the mTOR axis after B+I injury." (PMID 35955914, 2022). "Another proteotranscriptomics study, showed increased levels of phosphorylation of Akt, mTOR and other downstream effectors at 24h post-infection, indicating activation of Akt-mTOR pathway at an early stage of the infection." (PMID 36389723, 2022). "In relation to the immunosuppressive therapy, it was observed that no patient who presented a moderate-severe form of the disease, received immunosuppressive therapy which includes an mTOR inhibitor at the time of the diagnosis of infection." (PMID 35419375, 2022). "Our functional and network community analyses in the patient transcriptomics identified the coordination of biological signaling systems like FoxO, Notch and mTOR/HIF-1 signaling with metabolic pathways of CCEM during CCHFV-infection." (PMID 35437144, 2022). "The mammalian target of rapamycin (mTOR) is a highly conserved protein kinase that senses various stresses, such as hunger, oxidative stress, energy stress, and pathogen infection, and initiates autophagy." (PMID 35402295, 2022). "The mTOR pathway is involved in the infection of many DNA and RNA viruses and plays an important role in viral replication." (PMID 35438526, 2022). "MTOR-dependent autophagy was inhibited, as evidenced by mTOR phosphorylation and p62 accumulation at 48 h post-S.pn infection." (PMID 35111047, 2021). "Results were echoed in studies of human neuronal precursors and glial cells in culture in which ZIKV seems to induce autophagy early on during infection, but then downregulates autophagy through induction of mTOR in order to facilitate ZIKV replication." (PMID 37431450, 2021). "The initiation phase of HSCT-TMA pathogenesis results from endothelial injury caused by immunosuppressive agents such as calcineurin or mTOR inhibitors, acute GVHD, infection, or conditioning with cytotoxic agents and/or total body irradiation." (PMID 34924021, 2021). "Mammalian target of rapamycin (mTOR) knockdown cell lines were established by lentiviral infection with shmTOR." (PMID 35155187, 2021). "Authors showed the activation of AKT/mTOR signaling during initial phases of infection, and the inhibition of AKT by MK-2206 can suppress SARS-CoV-2 infection." (PMID 33920748, 2021). "The classical autophagy of the host is impaired by activating mTOR in the early stages of Leishmania infection, but at later stages of infection, autophagy is activated, which facilitates the survival of the parasite." (PMID 34900761, 2021). "Increases in macrophage numbers due to L-arginine or L-citrulline following infection were attenuated when inhibiting glycolysis or mTOR." (PMID 34054815, 2021). "To further elucidate the role of TLR2 in impaired autophagy by infection, we applied TLR2-deficient macrophages to observe the potential interaction between TLR2 and the AKT/mTOR pathway." (PMID 34900761, 2021). "Since previous studies showed a critical role of PI3K/mTOR pathway in KSHV pathogenesis during infection, lytic reactivation, and KSHV-induced tumorigenesis, we focused on the cell culture dependent modulation of this pathway." (PMID 33484281, 2021). "The mTORC1 pathway, including mTOR, p-mTOR, p-4E-BP1, p-S6K, were activated with Glu in APEC XM-infected bEnd.3 cells, and inactivated in the Glu deficiency medium during APEC XM infection." (PMID 34502151, 2021). "The mTOR signaling pathway can be targeted to block the infection and replication of viruses other than coronaviruses by inducing autophagy and inhibiting viral protein synthesis." (PMID 33768214, 2021). "Future studies are needed to explore the potential or limitation of mTOR/Akt-targeted therapeutics against infections with antibiotic resistant Mtb or NTM." (PMID 33828998, 2021).
infection (continued). "The mTOR-signaling pathway has also been used to block several other viruses’ infection and replications by inducing autophagy and inhibiting viral protein synthesis." (PMID 34179893, 2021). "In this study, the expression of signaling molecule mTOR was significantly down-regulated after infection with pathogens in the muscle." (PMID 33574492, 2021). "The mTOR signaling pathway is closely related to T-cell death-survival balancing in infection or stress 11-12." (PMID 34220329, 2021). "As everolimus is an mTOR inhibitor known to upregulate autophagy, the increased ability to control infection signifies the ability for everolimus to modulate the immune system through the mTOR pathway." (PMID 33966361, 2021). "The host kinase mechanistic target of rapamycin (mTOR), a cellular regulator of protein synthesis, growth, and motility, is coopted by influenza virus to promote infection." (PMID 33013775, 2020). "Ab4∆ORF1 infection resulted in upregulation of mTOR signaling, focal adhesion, and chemokine signaling pathway." (PMID 32911663, 2020). "The obligate intracellular parasite Toxoplasma gondii reprograms host gene expression through multiple mechanisms that promote infection, including the up-regulation of mTOR-dependent host mRNA translation." (PMID 33014898, 2020). "Here we show that infection with MCMV in a model of cytochrome oxidase c deficiency exacerbates the complex IV deficiency and mitochondrial dysfunction, causes alterations in mTOR signalling, and morphological changes in neuromuscular connections." (PMID 32130224, 2020). "The role of mTOR in cell survival and protein synthesis raises questions about its involvement in bacterial invasion and survival during infection." (PMID 32674261, 2020). "As we and others have previously demonstrated, infection by T. gondii increases host mTOR signaling and mTOR-dependent mRNA translation." (PMID 33014898, 2020). "Consistent with this, the transcriptome of human macrophages after 2 h of infection with A. fumigatus was markedly enriched in genes involved in mTOR signaling." (PMID 32385235, 2020). "Collectively, the data suggest a novel mechanism that IAV stimulates mTOR pathway at early stages of infection; however, at a later time-point, positive regulation of miR-101 restrains the mTOR expression, and hence, the viral propagation." (PMID 32326380, 2020). "We have demonstrated that this decline in glycolytic metabolism in exhausted Ag-expCD4+ T cells is related to the loss of T-bet expression, with Ag-expTh1 cells maintaining high levels of mTOR activity and glycolytic metabolism during infection." (PMID 32817333, 2020). "Elevated levels of miR-101, both during IAV infection, and NP transfection, regulated mTOR expression and suppressed viral replication at later stages of infection." (PMID 32326380, 2020). "This depends on the cell type and the pathogen involved as well as on the stage of infection and at which level mTOR signaling and metabolism is targeted." (PMID 31936570, 2020). "Cross-talks between cytokine and mTOR signaling pathways control inflammatory responses after pathogen infection." (PMID 32549342, 2020). "In the presence of infection, we identified downregulation of the mTOR signalling pathway via its downstream targets, S6 and 4EBP1, in the livers of Taco1 mutant mice." (PMID 32130224, 2020). "Listeria monocytogenes and Staphylococcus aureus stimulate mTOR by promoting activation of phosphoinositide 3-kinase/protein kinase B signaling pathways, which favor pathogen survival during infection." (PMID 32848049, 2020). "Similar to mTOR, the levels of p-Akt were increased during infection with Δku80 conidia, but less when the ΔpksP strain was used." (PMID 32385235, 2020). "In the heart mTOR signalling is upregulated upon infection, indicating that additional energy impost on the mutant mice activates the mTOR stress response in the heart, while in the liver mTOR signalling is downregulated." (PMID 32130224, 2020).